CXCL10 (C-X-C motif chemokine ligand 10)
Diseases named in the same sentence as CXCL10 in open-access papers (continued):
Sharing a sentence is not in itself a finding about the gene and the disease.
invasive carcinoma (2 papers, 2021 to 2022). A carcinoma that is not confined to the epithelium, and has spread to the surrounding stroma. "In the HR-negative subgroup, CXCL10 mRNA expression was significantly higher in invasive carcinoma compared to DCIS (p < 0.001), similar to the whole group." (PMID 34504204, 2021). "CXCL10 mRNA and protein expression was significantly higher in invasive carcinoma than in DCIS in the whole group and HR-negative tumors." (PMID 34504204, 2021). "In invasive carcinoma, CXCL10 mRNA expression also showed a weak positive correlation with TIL density (rho = 0.382, p = 0.003)." (PMID 34504204, 2021). "Increased number of PD-L1+ immune cell infiltration was associated with CXCL10 expression in both DCIS and invasive carcinoma in this study." (PMID 34504204, 2021). "In the present study, CXCL10 expression was significantly higher in invasive carcinoma than in DCIS." (PMID 34504204, 2021). "In invasive carcinoma, CXCL10 expression was more commonly observed compared to DCIS with 81 cases (21.8%) of CXCL10-positive tumors among 372 cases of invasive carcinomas (p < 0.001)." (PMID 34504204, 2021). "In HR-negative subgroup, CXCL10 expression was significantly higher in invasive carcinoma than DCIS (42.6% vs. 13.7%, p < 0.001)." (PMID 34504204, 2021). "In the whole group, expression of CXCL10 mRNA, evaluated by the fold change (2−ΔΔCt), was significantly higher in invasive carcinoma than in DCIS (p < 0.001)." (PMID 34504204, 2021). "Of the third set, 223 cases of DCIS and 151 cases of invasive carcinoma with data of immune cell infiltration were used to assess correlation of immune cell subset infiltration with CXCL10 expression." (PMID 34504204, 2021). "The difference in CXCL10 mRNA expression between DCIS and DCIS associated with invasive carcinoma (DCIS-INV) was also examined." (PMID 34504204, 2021). "Taken together, CXCL10 seems to induce tumor cell proliferation, migration, and immune cell infiltration, suggesting its critical role in the progression of DCIS to invasive carcinoma." (PMID 34504204, 2021). "The difference in CXCL10 expression between DCIS and invasive carcinoma was validated by real-time polymerase chain reaction (PCR) and immunohistochemistry." (PMID 34504204, 2021). "In invasive carcinoma, CD8+ and FOXP3+TIL infiltration as well as PD-L1+ immune cell infiltration was higher in CXCL10-positive tumors (p = 0.007, p = 0.001, and p = 0.001, respectively)." (PMID 34504204, 2021). "CXCL10 protein expression was evaluated in the third set compose of 223 cases of DCIS and 372 cases of invasive carcinoma." (PMID 34504204, 2021). "TIL infiltration had a positive correlation with CXCL10 expression in both DCIS and invasive carcinoma in this study." (PMID 34504204, 2021). "In conclusion, our study showed that among 770 immune related genes, CXCL10 revealed the highest difference in expression between DCIS and invasive carcinoma." (PMID 34504204, 2021). "CXCL10 mRNA expression was also evaluated in the invasive and DCIS components within the same tumor in the 24 cases of invasive carcinoma with a sufficient DCIS component." (PMID 34504204, 2021). "Therefore, using CXCL10 as a target molecule, we analyzed the role of CXCL10 in the progression of DCIS to invasive carcinoma." (PMID 34504204, 2021). "In DCIS, immunohistochemistry revealed that CXCL10 expression was not frequent; however, the staining pattern was similar to that of invasive carcinoma with dot-like cytoplasmic or membranous staining in tumor cells and immune cells, especially in macrophages." (PMID 34504204, 2021).
invasive carcinoma (continued). "We confirmed that CXCL10 mRNA expression was significantly higher in invasive carcinoma than in DCIS, especially in hormone receptor (HR)-negative tumors using a validation set." (PMID 34504204, 2021). "Using the second validation set of samples composed of 120 cases of DCIS and invasive carcinoma (60 cases in each), difference in CXCL10 mRNA expression was examined between DCIS and invasive carcinoma in the whole groups, in HR-positive subgroup, as well as in HR-negative subgroup." (PMID 34504204, 2021). "Moreover, this is the first large study comparing CXCL10 expression in DCIS and invasive carcinoma." (PMID 34504204, 2021). "However, the reason why CD4+ TIL infiltration differs in DCIS but not in invasive carcinoma in relation to CXCL10 expression needs further investigation." (PMID 34504204, 2021). "In HR-negative invasive carcinoma, FOXP3+TIL and PD-L1+ immune cell infiltration was also significantly higher in CXCL10-positive tumors than in CXCL10-negative tumors (p = 0.019 and p = 0.002, respectively)." (PMID 34504204, 2021). "Interestingly, in this study, CXCL10 expression was significantly different between DCIS and invasive carcinoma in HR-negative subgroup, but not in HR-positive subgroup." (PMID 34504204, 2021). "However, S100A8, LAG3, CXCL10, CXCL9 and BIRC5 showed a difference in fold change between DCIS and invasive carcinoma although statistically not significant (adjusted p value > 0.05)." (PMID 34504204, 2021).
Kaposi's sarcoma (2 papers, 2022). A malignant neoplasm characterized by a vascular proliferation which usually contains blunt endothelial cells. "Kaposi’s sarcoma cells released IL-6, IL-8, Ccl5, and Cxcl10 in response to long-term poly(I:C) exposure." (PMID 35737804, 2022). "The role of CXCL10 in inhibiting angiogenesis (angiostasis) has been extensively studied in various tissues and cancers, including the cornea, skeletal muscle cells and Kaposi sarcoma." (PMID 35346324, 2022).
keloid (2 papers, 2020 to 2025). An irregularly shaped, elevated mark on the skin caused by deposits of excessive amounts of collagen during wound healing. "Our results associate keloid tissues with an inflammatory milieu representing multiple T-helper pathways, including the Th2 (e.g. IL-4R, CCL11, TSLP, TNFSF4/OX40L, TNFRSF4/OX40), Th1 (e.g. IFNγ, CXCL10/11), Th17/Th22 (e.g. PI3, CCL20, S100As) axes, as well as the JAK/STAT signaling molecule JAK3." (PMID 33329590, 2020).
leukopenia (2 papers, 2024 to 2026). "Prior studies have shown that patients with anti-Ro52 and anti-Ro60 antibodies have higher rates of leukopenia and increased production of CXCL10, potentially contributing to a lowered vaccine efficacy in this subgroup." (PMID 38456511, 2024).
lower respiratory tract infection (2 papers, 2022 to 2026). "CXCL10 (IP-10) was also highly expressed in our analysis but was removed due to its high expression in other lower respiratory tract infections." (PMID 36561889, 2022).
meningeal TB (2 papers, 2012 to 2015). "Elevated CSF MIP-1α/CCL3 also occurs in bacterial and tuberculosis meningitis, and an increased CSF CCL3/CXCL10 ratio prior to ART initiation is associated with future cryptococcal-IRIS." (PMID 25651842, 2015). "Among potential clinical signatures reported are CXCL9, CXCL10, CCL1, and IL11, as their expression levels could differentiate some kinds of clinical manifestations such as latent TB, pulmonary, and meningeal TB." (PMID 22675550, 2012).
metastatic cancer (2 papers, 2023). A carcinoma which has spread from the original site of growth to another anatomic site. "This analysis showed that both mRNA and protein levels of CXCL10, CCl5 and IRF7 protein levels were elevated in metastatic cancer cells in culture and reduced in 66cl4-derived primary tumors." (PMID 36882786, 2023).
Mycobacterium infection (2 papers, 2017 to 2024). Infections with bacteria of the genus Mycobacterium. "As was reported, pathogen specific Th17 cells generated during mycobacterium infection induce the expression of CXCL9, CXCL10 and CXCL11, as well as IL-17 produced dictate the migration of other important effectors cell types to control the infection." (PMID 29259310, 2017).
nephrosis (2 papers, 2017 to 2018). Pathological processes of the KIDNEY without inflammatory or neoplastic components. "CXCL10, a member of the α (C-X-C) subfamily, has been reported to contribute to the severity of kidney diseases in several animal models of nephrosis." (PMID 29643988, 2018).
optic neuritis (2 papers, 2021 to 2024). Optic neuritis is inflammation of the optic nerve, the nerve that carries the visual signal from the eye to the brain.The conditionmay cause sudden, reduced vision in the affected eye(s). "Furthermore, concentrations of CXCL8, CXCL10 and CCL20 in sera did not significantly differ among subgroups of MS patients divided by presence or localization of demyelinating lesions (supratentorial, infratentorial and cervical), sex, or history of optic neuritis." (PMID 39125633, 2024).
orchitis (2 papers, 2017 to 2026). Inflammation of one or both testes due to viral or bacterial infections. "Understanding the mechanisms by which MuV induces CXCL10 production in the testes would be helpful for the development of therapeutic interventions in MuV orchitis." (PMID 29072682, 2017). "Whether CXCL10 upregulation facilitates the development of orchitis by recruiting leukocytes to the testes after MuV infection requires clarification in vivo." (PMID 29072682, 2017).
overactive bladder (2 papers, 2022). Symptom of overactive detrusor muscle of the urinary bladder that contracts with abnormally high frequency and urgency. "The cytokines with high diagnostic values to distinguish IC/BPS and overactive bladder included IL-10, RANTES, eotaxin, CXCL10, IL-12p70, NGF, IL-6, IL-17A, MCP-1, and IL-1RA." (PMID 35626252, 2022). "Using different urinary biomarkers including IL-10, RANTES, eotaxin, CXCL10, IL-12p70, NGF, IL-6, IL-17A, MCP-1, and IL-1RA, IC/BPS could be distinguished from overactive bladder." (PMID 36233356, 2022).
pertussis (2 papers, 2016 to 2022). A contagious bacterial respiratory infection caused by Bordetella pertussis. "Initial loss of CXCL10 or PGF2α signaling after immunization with the acellular pertussis vaccine (Tdap) may play a role in acquired pertussis immunity." (PMID 35214778, 2022). "Our current in vivo study demonstrated that immunization with an OMV-based pertussis vaccine (omvPV) in comparison to wPV elicited reduced concentrations of serum pro-inflammatory cytokines (IL-1α, IL-1β, and IL-6), chemokines (CXCL1 and CXCL10), and G-CSF." (PMID 27905535, 2016). "Stimulation of THP-1 cells with BscF alone initiated significant expression of CXCL10 and PGF2α but not when Tdap was used, suggesting that BscF might be an important pertussis antigen for next-generation pertussis vaccines or when combined with the current aP vaccine." (PMID 35214778, 2022).
plasmacytoma (2 papers, 2015 to 2022). Plasmacytoma is a localized mass of neoplastic monoclonal plasma cells that represents approximately 5% of all plasma cell neoplasms. "CXCL10 is highly expressed in mouse models of plasmacytoma and mammary adenoma, while it has low expression in mouse models without thymus; therefore, the anti-tumor effect of the CXCL10/CXCR3 pathway is thought to be T lymphocyte-dependent." (PMID 36479091, 2022). "CXCL10 also elicits a Th1 cell-dominated anti-tumour inflammatory response that can inhibit plasmacytoma growth." (PMID 26115406, 2015).
Pneumocystis infection (2 papers, 2010 to 2021). "Pneumocystis infection appears to be associated with dysfunction of the IL-23/IL-17 axis, with higher lung fungal burdens and reduced production of IL-17 and chemokines CXCL10 (IP-10), CCL3, CCL4, and CCL5, all crucial for infection resolution." (PMID 34829225, 2021).
polyp (2 papers, 2014 to 2023). A usually exophytic mass attached to the underlying tissue by a broad base or a thin stalk. "The decrease in serum adiponectin accompanied by increased levels of CXCL10 in subjects from the polyp and CRC groups as compared to volunteers from the control group is one of the main findings of the present study." (PMID 38003638, 2023). "Moreover, in the studied sample, CXCL10 levels increased and resistin levels decreased in CRC compared to the control and polyp groups, respectively." (PMID 38003638, 2023).
psittacosis (2 papers, 2022 to 2025). "We found significant upregulated expression of multiple chemokines and receptors (CXCL1, CXCL9, and CXCL10/IP-10) in severe psittacosis cases." (PMID 36119044, 2022).
pulmonary sarcoidosis (2 papers, 2016 to 2025). Sarcoidosis affecting the lung parenchyma. "CXCL11 and CXCL10 may play a role in the accumulation of Th1 cells in pulmonary sarcoidosis, a Th1-associated disease." (PMID 27776524, 2016).
relapsing-remitting MS (2 papers, 2022 to 2024). "A significant increase in CXCL10 was detected in the CSF of patients with relapsing-remitting MS in comparison with secondary progressive MS." (PMID 36490282, 2022).
reovirus infection (2 papers, 2011 to 2017). "Our data also demonstrate that cells with low reovirus infectivity (SK-LMS-1) induce CXCL10 to an equivalent extent to those that are more susceptible to reovirus infection (HT-1080)." (PMID 29156834, 2017).
retinitis (2 papers, 2022 to 2025). Inflammation of the retina. "The relative expression of IFNγ and IFNα (Both inducers of CXCL 9 and CXCL10) were elevated in case of patients with retinitis." (PMID 35538132, 2022). "The mean concentrations for HCMV viral load, TNFα and IL1β were significantly reduced in case of patients with end organ retinitis (HR), whereas the mean concentrations of TGFβ and CXCL10 were significantly higher in case of patients with retinitis." (PMID 35538132, 2022). "When mRNA expression pattern was compared between the two groups it showed that the expression of CXCL9 and CXCL10 was significantly higher in case of retinitis patients whereas that of CXCL11 was higher in case of the patients with gastro-enteric disease." (PMID 35538132, 2022). "Work in mouse experimental toxoplasmic encephalitis and retinitis has identified essential roles for CCL2 and CXCL10 in the recruitment of myeloid and lymphoid cell subsets into infected tissues." (PMID 40137771, 2025).
ROSAH syndrome (2 papers, 2022 to 2023). "Consistent with the observations in patients with ROSAH syndrome, knock-in mice with the Alpk1 T237M mutation had elevated serum levels of CXCL1, CXCL10 and CCL2." (PMID 35868845, 2022). "Patients with ROSAH syndrome also demonstrated elevations of additional cytokines and chemokines including plasma CXCL10 (interferon gamma-induced protein 10 (IP-10)) and serum CXCL1 (GRO-alpha (previously known as neutrophil-activating protein 3))." (PMID 35868845, 2022).
Rotavirus infection (2 papers, 2015 to 2017). Infection with any of the rotaviruses. "Of interest, several IFN inducible genes (OAS1, MX1, IL18, IITP3, TAP1, and RSAD2) as well as several cytokines and chemokines (CCL5, CXCL10, CXCL11, IL8, and CCL15) were upregulated by rotavirus infection." (PMID 28210256, 2017).
squamous cell carcinoma of the tongue (2 papers, 2014 to 2019). "A bioinformatics analysis suggested that CXCL10 and CXCL2 were members of the key molecules of epithelia in tongue squamous cell carcinoma." (PMID 30847302, 2019).
Ureteral obstruction (2 papers, 2014 to 2016). Obstruction of the flow of urine through the ureter. "Crisman and coworkers detected the expression of CCL2/MCP-1, CCL5/RANTES, and CXCL10/IP-10 at 1 day of unilateral ureteral obstruction in mice." (PMID 24692841, 2014).
urticaria (2 papers, 2022 to 2024). A vascular reaction of the skin characterized by erythema and wheal formation due to localized increase of vascular permeability. "Comparably, CCR5 and CXCL10, which were both also involved in the recruitment of eosinophils, were found to be significantly increased in both urticaria-affected samples when compared to healthy samples." (PMID 38932291, 2024).
(Ss) (1 paper, 2018). "To explore the association of Type III IFNs with Strongyloides stercoralis (Ss) infection, we examined the systemic levels of IFN lambda-1, IFN lambda-2 and IFN lambda-3, IL-10, and CXCL10/IP-10 in Ss infected (INF, n = 44), helminth—uninfected (UN, n = 44) and in post-treatment INF individuals." (PMID 30405603, 2018). "Next, we wanted to determine, whether parasite antigen induces expression of CXCL10/IP-10 in Ss infection." (PMID 30405603, 2018).
AA amyloidosis (1 paper, 2025). Secondary amyloidosis is a form of amyloidosis, that complicates chronic inflammatory disorders (mainly rheumatoid arthritis) and is characterized by the aggregation and deposition of amyloid fibrils composed of serum amyloid A protein, an acute phase reactant. "Additionally, several confounding factors are known for CXCL9 and CXCL10, including bacterial urinary tract infections, BK polyomavirus infection, recurrent AA amyloidosis, and thrombotic microangiopathy." (PMID 41306150, 2025).
acute hepatitis B virus infection (1 paper, 2023). A new infection by the hepatitis B virus, which can be transmitted by direct contact of infected blood with mucous membranes or open areas of the skin. "For instance, in humans, acute hepatitis B virus infection is accompanied by systemic cytokine and chemokine responses combined with increased serum CXCL10 level, which attracts more inflammatory cells to the liver and aggravates liver injury." (PMID 37693903, 2023).
acute monocytic leukemia (1 paper, 2025). Acute monoblastic leukemia (AML-M5), is one of the most common subtypes of acute myeloid leukemia (AML) that is either comprised of more than 80% of monoblasts (AML-M5a) or 30-80% monoblasts with (pro)monocytic differentiation (AML-M5b). "Additionally, phloridzin limits TNF‐α mRNA and IL‐8 expression, thereby suppressing CXCL10 production in LPS‐stimulated human acute monocytic leukemia cell lines." (PMID 40761486, 2025).
acute rheumatic fever (1 paper, 2024). "have reported that the level of CXCL10 is elevated in sera from patients with acute rheumatic fever, and CXCL10 could bind to CXCR3 of T cells to activate the release of GM-CSF from T cells." (PMID 38469144, 2024).
adenovirus infection (1 paper, 2018). "As for NF-kappaB signalling being responsible for CXCL10 expression, a recent report suggests that the induction of CXCL10 production adenovirus infection is mediated by the Akt activation pathway." (PMID 30001342, 2018).
alcoholic hepatitis (1 paper, 2020). Acute hepatitis resulting from ingestion of alcohol. "In contrast to human data where Ccl2, Ccl3, Ccl20 and Cxcl10 transcripts were significantly changed in alcoholic hepatitis compared to healthy control, none of these statistically significant changes were found in the murine models." (PMID 32051453, 2020).
amenorrhea (1 paper, 2023). The absence of menses in a woman who has achieved reproductive age. "In this study, we developed a CXCL10-based gene cluster model as a potential diagnostic biomarker for POF, a multifactorial and heterogeneous disease characterized by amenorrhea, decreased estrogen levels, and increased female gonadotropin levels." (PMID 38107572, 2023).
amyloid (1 paper, 2018). "CXCL10 seems to be implicated in the pathogenesis of AD, indeed authors showed that a deficiency in CXCR3 helped to prevent inflammation, and a lower amyloid burden and less cognitive dysfunctions have been observed in a mouse model of AD." (PMID 30092003, 2018).
amyloidoma (1 paper, 2024). Nodular localized form of amyloidosis with predominantly thoracic localization (pulmonary amyloidosis), considered as secondary protein structure disease in which insoluble protein fibrils accumulate extracellularly. "ALλ(CLA) amyloidomas contained significantly more CXCL10, GM-CSF (granulocyte monocyte-colony stimulating factor), and IL-10, with more expression of CCL5 trending towards significance (p=0.0882)." (PMID 39600710, 2024).